KRABD4 (KRAB domain containing 4)
Synonyms: KRBOX4; ZNF673; FLJ20344
Tractability: PROTAC: ubiquitination databases record sites on it.
Gene: Protein-coding gene on chromosome X (46,447,255 to 46,497,422, forward strand). Ensembl gene ENSG00000147121.
Subcellular location (Human Protein Atlas): Nucleoplasm
Pathways (Reactome):
Gene expression (Transcription): Generic Transcription Pathway
Gene Ontology:
Molecular function: DNA-binding transcription repressor activity, RNA polymerase II-specific; RNA polymerase II cis-regulatory region sequence-specific DNA binding
Biological process: negative regulation of transcription by RNA polymerase II; regulation of DNA-templated transcription
Cellular component: nucleus
Homologues: Orthologues: chimpanzee KRBOX4 (99% identical), macaque KRBOX4 (89% identical), dog ZNF674 (65% identical), pig ZNF674 (49% identical), mouse Zfp78 (26% identical), Drosophila melanogaster CG3281 (16% identical), Drosophila melanogaster CG2712 (15% identical), Drosophila melanogaster Phs (15% identical). Paralogues in human: ZNF674 (81% identical), ZFP90 (40% identical), ZNF614 (36% identical), ZNF10 (35% identical), ZFP69 (31% identical), ZNF248 (31% identical), ZFP69B (30% identical), ZNF805 (29% identical), ZNF264 (28% identical), ZNF599 (28% identical), ZNF778 (28% identical), ZNF582 (27% identical), and 50 more.
Diseases named in the same sentence as KRABD4 in open-access papers:
KRABD4 is named in the same sentence as 2 diseases in open-access papers, as found by Europe PMC text mining. Sharing a sentence is not in itself a finding about the gene and the disease.
KRABD4 shares sentences with these, for which no sentence is quoted: cognitive deficit (1 paper); schizophrenia (1).